NOP14 (NOP14 nucleolar protein)
Description:
Involved in nucleolar processing of pre-18S ribosomal RNA. Has a role in the nuclear export of 40S pre-ribosomal subunit to the cytoplasm (By similarity).
Synonyms: C4orf9; NOL14; RES4-25; UTP2; RES425
Tractability: PROTAC: ubiquitination databases record sites on it; its protein half-life has been measured.
Gene: Protein-coding gene on chromosome 4 (2,937,933 to 2,963,406, reverse strand). Ensembl gene ENSG00000087269.
Subcellular location: Nucleus, nucleolus
Subcellular location (Human Protein Atlas): Nucleoli; Nucleoplasm
Pathways (Reactome):
Metabolism of RNA: Major pathway of rRNA processing in the nucleolus and cytosol; rRNA modification in the nucleus and cytosol
Gene Ontology:
Molecular function: enzyme binding; RNA binding; snoRNA binding
Biological process: protein localization to nucleolus; ribosomal small subunit biogenesis; endonucleolytic cleavage in 5'-ETS of tricistronic rRNA transcript (SSU-rRNA, 5.8S rRNA, LSU-rRNA); endonucleolytic cleavage in ITS1 to separate SSU-rRNA from 5.8S rRNA and LSU-rRNA from tricistronic rRNA transcript (SSU-rRNA, 5.8S rRNA, LSU-rRNA); endonucleolytic cleavage to generate mature 5'-end of SSU-rRNA from (SSU-rRNA, 5.8S rRNA, LSU-rRNA); maturation of SSU-rRNA; maturation of SSU-rRNA from tricistronic rRNA transcript (SSU-rRNA, 5.8S rRNA, LSU-rRNA); rRNA processing
Cellular component: membrane; nucleolus; nucleoplasm; 90S preribosome; Noc4p-Nop14p complex; small-subunit processome
Genetic constraint (gnomAD): Loss-of-function variants: 54 observed, 96.62 expected, observed/expected ratio (o/e) 0.56, 90% interval 0.45 to 0.7. The upper end of that interval is the gene's LOEUF score, 0.7, which puts it in group 2 of 6, group 1 being the genes least tolerant of losing a copy. Missense variants: 1,107 observed, 1,082.2 expected, observed/expected ratio (o/e) 1.02, 90% interval 0.97 to 1.08. Synonymous variants: 420 observed, 422.4 expected, observed/expected ratio (o/e) 0.99, 90% interval 0.92 to 1.08.
Homologues: Orthologues: macaque NOP14 (96% identical), chimpanzee NOP14 (95% identical), mouse Nop14 (83% identical), rat Nop14 (81% identical), dog NOP14 (80% identical), guinea pig NOP14 (79% identical), pig NOP14 (78% identical), rabbit NOP14 (73% identical), tropical clawed frog nop14 (60% identical), zebrafish nop14 (37% identical), Drosophila melanogaster l(3)07882 (34% identical), Caenorhabditis elegans nol-14 (30% identical).
Diseases named in the same sentence as NOP14 in open-access papers:
NOP14 is named in the same sentence as 30 diseases in open-access papers, as found by Europe PMC text mining. Sharing a sentence is not in itself a finding about the gene and the disease. The quoted sentences say what the papers report.
pancreatic cancer (6 papers, 2015 to 2023). "Our previous study also showed that NOP14 was significantly upregulated and associated with poorer prognosis in patients with pancreatic cancer." (PMID 37506248, 2023). "In our previous studies, NOP14 was found overexpressed in primary pancreatic cancer or metastases, which was significantly associated with poor prognosis." (PMID 37506248, 2023). "For example, NOP14 promoted proliferation and metastasis of pancreatic cancer cells, and loss of CADPS was associated with poor prognosis of malignant embryonal brain tumors." (PMID 35406793, 2022). "Next, to validate this finding, we analyzed the expression of NOP14 in various pancreatic cancer cells in protein separation assay followed by Western blotting." (PMID 37506248, 2023). "To explore the effect of NOP14 dysregulation on cancer cell proliferation, we first analyzed the correlation between NOP14 level and cell proliferation in four commonly used pancreatic cancer cell lines." (PMID 37506248, 2023). "In this study, we first investigated the subcellular localization and expression of NOP14 by multiple quantitative assays in pancreatic cancer." (PMID 37506248, 2023). "The site of RFP-NOP14 expression was consistent with that of nucleolar protein B23, indicating that NOP14 was mainly expressed in the nucleolar with a little diffused in the nucleoplasm of pancreatic cancer cells." (PMID 37506248, 2023). "In this study, we found that NOP14 is localized mainly in cell nuclei in pancreatic cancer tissues by immunohistochemical analysis." (PMID 37506248, 2023). "To study the molecular mechanism of NOP14 in pancreatic cancer, we previously overexpressed and silenced NOP14 in PANC-1 cells and performed transcriptome sequencing to construct a map of NOP14 downstream target genes." (PMID 37506248, 2023). "In this study, we first used immunofluorescence and nuclear-cytoplasmic separation assay to assess the localization and expression of NOP14 in pancreatic cancer cells." (PMID 37506248, 2023). "Taken together, these results suggest that miR17-5p mediates the regulatory effect of NOP14 on pancreatic cancer cell proliferation." (PMID 37506248, 2023). "The proliferation assay showed a similar increase in proliferating ability in pancreatic cancer cell lines, indicating a positive correlation of proliferating ability with the expression of NOP14." (PMID 37506248, 2023). "To further study the nuclear localization of NOP14, we assessed its subcellular expressed location of NOP14 in pancreatic cancer cells by immunofluorescence analysis." (PMID 37506248, 2023). "Taken together, these results indicate that the NOP14 protein is localized mainly in the nucleus in pancreatic cancer cells." (PMID 37506248, 2023). "In this study, the localization of NOP14 in pancreatic cancer cells was studied by immunofluorescence and protein separation quantitative analyses." (PMID 37506248, 2023). "In contrast, NOP14 was rarely detected in the cytoplasm in any of those pancreatic cancer cell lines." (PMID 37506248, 2023). "Next, we explored correlation between E2F4, CCNE1, CCND1 and NOP14 in pancreatic cancer tissue in TCGA database." (PMID 37506248, 2023). "Subsequent functional study revealed that NOP14 overexpression was able to promote pancreatic cancer cell proliferation and metastasis both in vitro and in vivo." (PMID 26213846, 2015). "We confirmed that NOP14 was mainly localized in nucleolus in human pancreatic cancer cells." (PMID 37506248, 2023). "Based on these results, we speculated that NOP14 might regulate the proliferation of pancreatic cancer cells by inducing miR17-5p expression." (PMID 37506248, 2023). "This might explain the oncogenic roles of NOP14 in pancreatic cancer." (PMID 37506248, 2023).
pancreatic cancer (continued). "In addition, an opposite effect of NOP14 has been reported that NOP14 can promote tumorigenesis and metastasis of pancreatic cancer cells, suggesting that the responsive genes downstream of NOP14 may differ among different types of cancer." (PMID 26213846, 2015). "In conclusion, we reported the nucleolus localization and pro-proliferative effect of NOP14 by simultaneously activating downstream miR17-5p and E2F4 signaling in human pancreatic cancer." (PMID 37506248, 2023). "Obviously, NOP14 was substantially detected in nucleus and its level was successively increased in AsPC1, BxPC3, Mia PaCa2 and PANC1, which was in lines with our previous report on total protein in relevant pancreatic cancer cell lines." (PMID 37506248, 2023).
ovarian carcinoma (5 papers, 2014 to 2021). A malignant neoplasm originating from the surface ovarian epithelium. "In clinical studies of patients with ovarian cancer, downregulation of NOP14 was associated with a significantly worse survival rate." (PMID 32828126, 2020). "It has also been shown that LYAR, PDIA3, NOP14, NCALD, MTSS1 and CYP1B1 are correlated with the prognosis of ovarian cancer." (PMID 34696677, 2021). "In addition, LYAR and five other genes (PDIA3, NOP14, NCALD, MTSS1, and CYP1B1) showed potential as prognostic biomarkers for radical ovarian cancer." (PMID 34696677, 2021). "A gene expression profile study with whole blood cell mRNA from ovarian cancer patients revealed LYAR and other five genes (PDIA3, NOP14, NCALD, MTSS1 and CYP1B1) as potential prognostic biomarkers for curative and postoperative supportive therapies for ovarian cancer." (PMID 26413750, 2015).
melanoma (4 papers, 2020 to 2024). A malignant, usually aggressive tumor composed of atypical, neoplastic melanocytes. "This study elucidated the critical role and underlying mechanisms of NOP14 in melanoma CSC development." (PMID 35282769, 2022). "In contrast, some studies have reported that NOP14 inhibits melanoma by regulating the Wnt/β-catenin pathway and cancer stemness and inhibits breast cancer by inhibiting the NRIP1/Wnt/β-catenin pathway." (PMID 37441804, 2023). "The Wnt signaling activator BML-284 alleviated the effect of NOP14 overexpression on the stemness and function of melanoma CSCs." (PMID 35282769, 2022). "In summary, our results demonstrated that NOP14 overexpression affects the stemness and functions of melanoma CSCs." (PMID 35282769, 2022). "This study aimed to investigate the role and mechanism of NOP14 in the stemness and function of melanoma CSCs in vitro." (PMID 35282769, 2022). "The Wnt signaling activator BML-284 also alleviated the effect of NOP14 overexpression on the stemness and function of melanoma cells." (PMID 35282769, 2022). "Our previous studies suggested that the NOP14 nucleolar protein (NOP14) is involved in melanoma pathogenesis regulation." (PMID 35282769, 2022). "NOP14 overexpression suppressed melanoma cell stemness, reduced migration, invasion, and angiogenesis-inducing capabilities of melanoma CD133+ SLCs." (PMID 35282769, 2022). "In conclusion, our results showed that NOP14 suppresses the stemness and function of melanoma SLCs by inactivating Wnt/β-catenin signaling." (PMID 35282769, 2022). "In conclusion, NOP14 suppresses the stemness and function of melanoma SLCs by inactivating Wnt/β-catenin signaling." (PMID 35282769, 2022). "Li and colleagues reported that NOP14 suppresses the stemness and functions of melanoma CSCs through the inactivation of the Wnt/β-catenin intracellular signaling; specifically, its overexpression significantly impairs proliferation, migration and the proangiogenic potential of these cells." (PMID 39199632, 2024). "The NOP14 nucleolar protein is known to be involved in the regulation of melanoma pathogenesis." (PMID 39199632, 2024). "Furthermore, NOP14 overexpression can significantly inhibit melanoma cell growth, migration, and invasion and can increase the level of apoptosis." (PMID 35282769, 2022). "This suggested that NOP14 overexpression reduced the proportion of melanoma CSCs." (PMID 35282769, 2022). "NOP14 overexpression also inactivated Wnt/β-catenin signaling in melanoma CD133+ SLCs." (PMID 35282769, 2022). "Therefore, our results support the notion that NOP14 suppresses the stemness and function of melanoma SLCs by inactivating Wnt/β-catenin signaling." (PMID 35282769, 2022). "Therefore, in this study, we aimed to explore the role of NOP14 in the stemness and function of CSCs in melanoma in vitro." (PMID 35282769, 2022). "NOP14 overexpression subsequently decreased the proportion of CD133+ SLCs, impaired the colony-forming capabilities, and downregulated the expression of Nanog, SOX2, and OCT4 stem cell markers in A375 and A875 cells, suggesting that NOP14 suppresses the stemness of melanoma SLCs." (PMID 35282769, 2022). "NOP14 overexpression suppressed the migration and invasion of melanoma CD133+ SLCs." (PMID 35282769, 2022). "We hypothesized that NOP14 might affect melanoma CSC stemness and function via the Wnt/β-catenin signaling pathway." (PMID 35282769, 2022). "NOP14 overexpression impaired the induction of angiogenesis in melanoma CD133+ SLCs." (PMID 35282769, 2022). "NOP14 overexpression inactivated Wnt/β-catenin signaling in melanoma CD133+ SLCs." (PMID 35282769, 2022). "In addition, NOP14 can reduce melanoma cell proliferation and metastasis by regulating the Wnt/b-catenin signalling pathway." (PMID 32828126, 2020). "Thus, NOP14 is a novel target for CSC treatment in melanoma." (PMID 35282769, 2022). "Thus, NOP14 overexpression inactivated Wnt/β-catenin signaling in melanoma CD133+ SLCs." (PMID 35282769, 2022).
melanoma (continued). "Thus, we speculate that NOP14 may function through a suppressive effect on stemness in melanoma CSCs." (PMID 35282769, 2022). "Thus, NOP14 may play an important role in the occurrence and development of melanoma tumors." (PMID 35282769, 2022). "Therefore, we hypothesized that NOP14 could function as a metastasis suppressor in melanoma CSCs." (PMID 35282769, 2022).
bladder cancer (2 papers, 2020 to 2021). "miR-502-5p inhibited the expression of CCND1, NOP14, and DNMT3B, the targets of miR-502-5p, by reducing cell migration in bladder cancer." (PMID 34288816, 2021).
breast carcinoma (2 papers, 2015 to 2023). "Consistent with the tumor suppressor role of NOP14 in breast cancer, survival analysis suggested that low NOP14 expression is associated with poor patient outcome." (PMID 26213846, 2015). "In addition, NRIP1 has been reported negatively correlated with breast cancer through a genome-wide association study (rs2823093; P = 1.1 × 10−12), supporting the possible roles of NOP14 and NRIP1 in breast cancer development." (PMID 26213846, 2015). "High levels of NOP14 mRNA and protein were observed in the fibrocystic breast cell line MCF10A; whereas the levels of NOP14 mRNA and protein were low in the four breast cancer cell lines including MCF7, MDA-MB-231, MDA-MB-453 and BT474." (PMID 26213846, 2015). "Here, we show that NOP14 is poorly expressed in breast cancer cells and invasive breast cancer tissues." (PMID 26213846, 2015). "Survival analysis indicated that low NOP14 expression was significantly associated with poor overall survival (P = 0.0006) and disease-free survival (P = 0.0007), suggesting that NOP14 is a potential prognostic factor in breast cancer." (PMID 26213846, 2015). "Transfection of NOP14 cDNA significantly reduced the colony and sphere formation of breast cancer cells compared with those transfected with control vector." (PMID 26213846, 2015). "In vivo and in vitro studies indicated that NOP14 suppressed the tumorigenesis and metastasis of breast cancer cells." (PMID 26213846, 2015). "Finally, the NOP14 expression with respect to prognosis of breast cancer patients was also evaluated." (PMID 26213846, 2015). "These suggest that NOP14 expression may be an applicable prognostic biomarker for breast cancer." (PMID 26213846, 2015). "Moreover, Western blot analysis of the proteins participating in the Wnt/β-catenin pathway showed that the levels of NRIP1, β-catenin and GSK-3β phosphorylation were elevated by NOP14-overexpressing in three breast cancer cell lines (MDA-MB-231: ER-negative; MCF7 and BT474: ER-positive)." (PMID 26213846, 2015). "Moreover, NOP14 is one of the proteins that interact with PAXIP1, which contains tandem breast cancer carboxy-terminal domains and regulates multiple aspects of the cellular response to DNA damage, such as cell survival and differentiation." (PMID 26213846, 2015). "By contrast, transwell assays indicated that depletion of NRIP1 by siRNAs in cells with or without NOP14 overexpression promoted the migration and invasion of breast cancer cells." (PMID 26213846, 2015). "As CD44+/CD24−/low is the classic stem cell marker in breast cancer, and approximately 99% of MDA-MB-231 cells are CD44+, we focused on the level of CD24 in MDA-MB-231 cells with or without NOP14 overexpression." (PMID 26213846, 2015).
colorectal cancer (2 papers, 2022 to 2023). A primary or metastatic malignant neoplasm that affects the colon or rectum. "Zhu discovered that NOP14 regulates the NRIP1/GSK-3β/β-catenin signalling pathway to promote colorectal cancer proliferation and migration." (PMID 37441804, 2023).
acute lymphoblastic leukaemia (1 paper, 2023). "As Volker reported, vioprolide A, a natural product, has an outstanding therapeutic effect for acute lymphoblastic leukaemia by targeting NOP14 expression to affect ribosome biogenesis." (PMID 37441804, 2023).
adrenocortical carcinoma (1 paper, 2022). "Whereas in brain lower grade glioma (LGG), liver hepatocellular carcinoma (LIHC), sarcoma (SARC), adrenocortical carcinoma (ACC), high expression levels of NOP14 were associated with a poor prognosis (HR > 1, p < 0.05)." (PMID 35473611, 2022).
bladder urothelial carcinoma (1 paper, 2022). "In our study, we showed that NOP14 expression was significantly elevated in many kinds of cancer, such as bladder urothelial carcinoma, cholangiocarcinoma, and liver hepatocellular carcinoma." (PMID 35473611, 2022).
chronic nasopharyngitis (1 paper, 2024). "A total of 132 paraffin-embedded human NPC biopsies were subjected to immunohistochemical analysis, revealing stronger NOP14 staining in NPC lesions compared to chronic nasopharyngitis tissues." (PMID 38272224, 2024).
colon adenocarcinoma (1 paper, 2022). "For example, in colon adenocarcinoma (COAD), stomach adenocarcinoma (STAD), rectum adenocarcinoma (READ), and kidney renal clear cell carcinoma (KIRC), high NOP14 expression levels were associated with a good prognosis (HR < 1, p < 0.05)." (PMID 35473611, 2022).
ductal carcinomas in situ (1 paper, 2015). "Compared with the normal mammary tissue, strong NOP14 expression was detected in the fibrocystic tissue with atypical ductal hyperplasia (ADH), as well as in lobular and ductal carcinomas in situ." (PMID 26213846, 2015).
influenza (1 paper, 2022). An acute viral infection of the respiratory tract, occurring in isolated cases, in epidemics, or in pandemics; it is caused by serologically different strains of viruses (influenzaviruses) designated A, B, and C, has a 3-day incubation period, and usually lasts for 3 to 10 days. "Nevertheless, it is compelling that NLS2 has a nucleolar localization role in both influenza NP and human NOP14." (PMID 36230922, 2022).
Sepsis (1 paper, 2023). Sepsis is defined as life-threatening organ dysfunction caused by a dysregulated host response to infection. "The human nucleolar protein 14 (NOP14) gene has been reported previously to be located on chromosome 4p16.317 and is a key gene in the process of sepsis." (PMID 37749550, 2023). "Thus, the expression levels of the eight RBPs (DDX24, CBFA2T2, NOP14, ILF3, DNMT1, FTO, PPRC1, and NOLC1) were altered in the patients with sepsis might potentially be useful as novel biomarkers as well as targets to facilitate the diagnosis and management of sepsis." (PMID 37749550, 2023).